MGMT (O-6-methylguanine-DNA methyltransferase)
Diseases named in the same sentence as MGMT in open-access papers (continued):
Sharing a sentence is not in itself a finding about the gene and the disease.
tumor (continued). "Temozolomide (TMZ) is the standard first-line chemotherapeutic drug for treatment of GBM; however, its effectiveness is hindered by factors such as the overexpression of O6-methylguanine DNA methyltransferase (MGMT) and the existence of various genetic mutations and repair mechanisms in tumor cells." (PMID 41509117, 2025). "The MGMT gene encodes for a DNA repair enzyme that can mitigate tumor cell apoptosis." (PMID 39992790, 2025). "Interestingly, in patients with GBM treated with radiotherapy and TMZ, the presence of the concurrent methylation of both MGMT and Keap1 promoters was associated with a lower risk of tumor progression." (PMID 40298811, 2025). "In the context of GBM, MGMT promoter methylation is typically associated with a better response to alkylating chemotherapy, as the reduced expression of MGMT allows these drugs to induce more effective DNA damage in tumor cells, leading to cell death." (PMID 40722849, 2025). "Additionally, MGMT promoter methylation and radical tumor resection were independently associated with improved OS in the multivariate model." (PMID 41226912, 2025). "Knocking down MGMT might boost tumor mutational burden and enhance immune system recognition, potentially improving immune checkpoint inhibitor responses." (PMID 40895460, 2025). "Notably, the inverse association between the HALLMOUNT score and protective molecular features, including IDH mutations and MGMT promoter methylation, suggests that the score captures both systemic vulnerability and intrinsic tumor aggressiveness." (PMID 41470234, 2025). "The loss of MGMT-mediated DNA repair may make tumor cells more vulnerable to DNA strand breaks induced by radiotherapy, offering a possible explanation for better treatment outcomes in methylation-positive patients." (PMID 40895460, 2025). "Tumor grade, MGMT promoter methylation, and Ki-67 expression were associated with SAP." (PMID 39049072, 2024). "MGMT promoter methylation was also associated with frontal lobe tumour location." (PMID 39767640, 2024). "Furthermore, IDH1 and TERT mutations, 1p19q codeletion and MGMT methylation status were shown to be independently associated with tumour growth, providing molecular basis for the worse outcome." (PMID 38802734, 2024). "Regulation of GBM TMZ sensitivity is reportedly associated with genome repair systems in tumor cells, including O6-methylguanine-DNA methyltransferase (MGMT)-mediated demethylation, the base excision repair (BER) system, mismatch repair (MMR) and other activities." (PMID 38177123, 2024). "IDH mutations and MGMT promoter methylation should be checked in tumour samples." (PMID 37881322, 2023). "Furthermore, the accumulation of DNA damage caused by the inhibition of MGMT expression led to the apoptosis of tumor cells." (PMID 38071213, 2023). "A lower expression of the enzyme methylguanine-DNA-methyltransferase (MGMT) and hypermethylation of its promoter in tumour tissue have been associated with a better response to TMZ in some small studies, but these findings have not been validated in larger studies." (PMID 37720528, 2023). "Tumor progression is a hallmark in GB because recurrent GBs are driven by intrinsic (e.g., MGMT upregulation and increased tumor mutation burden) and extrinsic (e.g., hypoxia and immuno-suppressive tumor microenvironments) mechanisms developing resistance to therapies." (PMID 36980659, 2023). "IDH mutations and MGMT promoter methylation should be checked in tumor samples." (PMID 37881322, 2023).
tumor (continued). "For example, while an MGMT promoter unmethylated isocitrate dehydrogenase (IDH) wild type (WT) GBM patient is likely to succumb to the disease within a year, patients with an IDH-mutated, highly MGMT promoter methylated tumour have a fair chance at living beyond 5 years." (PMID 35454848, 2022). "Those sub-groups could be linked to the genetic status of tumours, such as the MGMT status or other mutations, associated with a better therapeutic response and prognosis." (PMID 36227862, 2022). "We propose that patients’ survival risk may be dependent on both the presence of MGMT promoter methylation and the stem cell level within the tumor." (PMID 36333778, 2022). "Thus, the initial step for exploring the prognostic role of the MGMT promoter methylation status in the present study was the detection of IDH1/2 mutations in tumor samples by Sanger sequencing." (PMID 36361838, 2022). "Factors significantly associated with longer OS were younger age, higher KPS, frontal versus multifocal tumor location, gross total resection, MGMT hypermethylation, IDH mutation, simultaneous plus sequential TMZ versus no TMZ administration, no steroid administration and salvage treatment." (PMID 34940951, 2022). "Loss of MGMT expression, associated with methylation of its promoter, defines a subset of HCCs and has been reported in tumour‐adjacent tissue from HCC patients; however, this loss of expression was without associated promoter hypermethylation as measured using methylation‐specific PCR." (PMID 34863035, 2022). "Future work will focus on defining whether MGMT loss is more associated with tumour emergence, or progression." (PMID 34863035, 2022). "OS was compared for a variety of subsets defined by the patient (age, KPS), tumor characteristics (MGMT promoter methylation and IDH1/2 mutation status), or anti-cancer therapy (number and cell composition of vaccinations received, TTF and/or bevacizumab use, and corticosteroid use)." (PMID 36517865, 2022). "Furthermore, as most elevated indexes occur in unmethylated GBM variants, a correlation with molecular data on MGMT methylation for possible cutoff limit verification and tumor biological behavior should be encouraged." (PMID 35822134, 2022). "In addition to using the level of MGMT as a reference for tumor treatment, genetic mutations and small molecule RNA also provide potential entry points for tumor treatment." (PMID 36060980, 2022). "KPS was reported or could be extracted in 7 studies, IDH mutational status in 5, MGMT hypermethylation in 3, age in 9, tumor location in 10, tumor volume in 10, hospital stay in 5 and adjuvant treatment in 7 studies." (PMID 33477796, 2021). "At this juncture, the pending correlative analyses from the prospective randomized phase II ECOG 2211 study may best reveal the true association between the tumor MGMT expression status and response to temozolomide." (PMID 34638356, 2021). "T2 tumours also harboured recurrent loss of chromosome 10q arm including the loci of MGMT." (PMID 33536587, 2021). "Loss of O-6-methylguanine-DNA-methyltransferase activity may favor the carcinogenetic action of exogenous alkylating agents and promote tumor development." (PMID 33919851, 2021). "In addition, many previous studies have shown that genotype, such as IDH mutation, 1p19q codeletion and MGMT promoter methylation status, has a great correlation with therapeutic effect and tumor prognosis." (PMID 34869030, 2021). "It cannot be ruled out that the two patients concerned may have been predisposed to the premature death, e.g. by virtue of their tumour biology including unmethylated MGMT status." (PMID 33623076, 2021). "Decreased MGMT expression in tumor cells was considered to be associated with increased risks of carcinogenesis and could induce much higher tumor cell proliferation." (PMID 33287738, 2020).
tumor (continued). "Since the lesions of our patient shrank dramatically after TMZ treatment, we were led to speculate that MGMT promoter hypermethylation is ubiquitous in tumor tissues, and the factors causing hypermethylation exist in the early stage of the tumor development." (PMID 32132978, 2020). "To determine if the observed heterogeneity was a direct consequence of established molecular subtypes in GBM, we performed cross-platform analyses using RNA (expression profiling) and DNA (IDH1 mutation and MGMT promoter methylation) isolated from matched tumor tissue." (PMID 32312953, 2020). "Chemotherapy with Temozolomide (TMZ), the most used drug in GB treatment, shows acquired resistance caused by the high levels of activity of DNA repair enzyme O6-methylguanine DNA methyltransferase (MGMT) in tumor cells that reduces the effect of this alkylating agent." (PMID 32019099, 2020). "The status of MGMT promoter methylation is associated with tumor response to TMZ therapy." (PMID 33041980, 2020). "Since IDH mutation status is both associated with tumor localization and MGMT methylation status, it may function as a confounding factor." (PMID 32477929, 2020). "It has been reported that high MGMT expression in tumor cell is associated with the resistance to 1,3- bis- (2-chloroethyl) -1- nitrosourea (BCNU) and temozolomide (TMZ), which target the O6-position of guanine, resulting in cytotoxic and mutagenic DNA adducts." (PMID 33628188, 2020). "However, risk stratification according to genetic profiles such as MGMT promoter methylation or IDH gene mutation of the tumor demonstrated a subgroup of patients, although a minority, shows an unexpected long-term survival for GBM." (PMID 32375876, 2020). "In addition, the loss of MGMT in tumor cells, including pancreatic neuroendocrine neoplasms, was reported to increase the therapeutic efficacy of DNA-alkylating agents, including STZ." (PMID 33287738, 2020). "Methylguanine DNA methyltransferase (MGMT) (the enzyme responsible for guanine methylation that endorses DNA repairing) expression in tumor tissue might help to screen responders: protein deficiency determines response to temozolomide in pancreatic NENs." (PMID 31273555, 2019). "Some image biomarkers may now be informative for predicting MGMT promoter methylation status or prognosis of glioblastoma, for prognosis for breast cancer, and for predicting EGFR mutation status or prognosis of non-small cell lung cancer." (PMID 30082856, 2018). "Cytosine methylation in different areas of the genome, as in the case of the MGMT promoter, has specific patterns associated with race and environmental factors such as diet quality and its effect on the behaviour of the neoplasia may differ according to race." (PMID 29515653, 2018). "MGMT promoter methylation was associated with tumor location and necrosis (P < 0.05)." (PMID 29467012, 2018). "have associated the tumor-suppressive role of miRNA-370 in GBM with the targeting of MGMT." (PMID 30497054, 2018). "Meanwhile, status of MGMT promoter methylation is associated with tumor response to TMZ therapy." (PMID 29619003, 2018). "Furthermore, methylation of the CpG islands of the MGMT promoter has shown to correlate with loss of MGMT protein expression in tumor tissue." (PMID 29344904, 2018). "However, if a tumor cell expresses O6-alkylguanine DNA alkyltransferase encoded in humans by the O-6-methylguanine-DNA methyltransferase (MGMT) gene, it can repair this type of DNA damage, and thus diminishes the therapeutic efficacy of TMZ." (PMID 28978179, 2017).
tumor (continued). "To gain further insight into the value of MGMT as a biomarker, we investigated the association of MGMT expression with various clinicopathological indicators, including age (greater than the median age), gender, tumor size, and functional status." (PMID 28152515, 2017). "Low MGMT immunoexpression potentially increases mutagenesis, which may cause tumor formation and an increased cellular proliferation rate." (PMID 28900805, 2017). "Our meta-analysis results suggested that lower expression of MGMT was associated with PA recurrence, suggesting that MGMT expression could be used as a marker of poor prognosis and tumor recurrence for patients with PA." (PMID 28152515, 2017). "The roles of reactive astrocytes, tumor associated microglia and macrophages, metabolic alterations, microsatellite instability, O6-methylguanine DNA methyltransferase (MGMT) DNA repair and epigenetic alterations mediated by the isocitrate dehydrogenase 1 (IDH1) mutations have been discussed." (PMID 28346397, 2017). "Thus, the associations of MGMT expression with drug resistance in tumor cells remain to be clarified in veterinary medicine." (PMID 29061940, 2015). "However the IDH mutation status and the MGMT methylation data from the tumour at presentation were still found to be of prognostic significance." (PMID 24952577, 2014). "There was an association between IDH1 mutations and MGMT methylation (higher IDH1 mutation rates in methylated tumours) across all tumour grades; this was statistically significant (Fisher’s exact test, p <0.01) for both AOA/AA and GB patients, but was most marked in the AOAs and AAs." (PMID 24952577, 2014). "Felsberg and colleagues speculated, that treatment with TMZ promotes survival of tumor cells with unmethylated MGMT status which give rise to resistant clones causing relapse." (PMID 23704990, 2013). "In this small series, MGMT protein was associated with less aggressive tumor characteristics." (PMID 22214427, 2012). "Notably, tumors with the enhanced expression of HOX genes, high EGFR expression plus unmethylated MGMT were associated with short survival, suggesting the involvement of a tumor stem-cell phenotype in the escape of tumor cells from radio-chemotherapy." (PMID 24212792, 2011). "The critical role of MGMT in DNA repair suggests that defective DNA repair may be correlative in the observed association between MGMT promoter methylation and tumor recurrence." (PMID 19807915, 2009). "Thus, the presence or absence of MGMT is considered a prognostic factor for GBM patients, as tumor cells with epigenetic silencing of the Mgmt promoter (i.e., MGMT-methylated) are more susceptible to DNA damage than those that express Mgmt (i.e., MGMT-unmethylated)." (PMID 40909807, 2025). "Studies suggest that MGMT methylation status may be potentially linked to aberrant activation of the VEGF pathway in the tumor microenvironment, with methylated tumors potentially exhibiting greater dependence on angiogenesis, thereby increasing sensitivity to VEGF inhibitors like BEV." (PMID 40963873, 2025). "FC between the tumor region and the dorsal attention network was associated with longer OS (HR, 0.88; 95%CI, 0.80–0.97; P = .007), and showed an independent association with OS (HR, 0.90; 95%CI, 0.81–0.99; P = .033) in a model including clinical factors, tumor volume and MGMT." (PMID 40084168, 2025). "The absence of this molecular variable limits our ability to disentangle whether the observed association between peri-operative hematologic dynamics—especially the Δ leukocyte-to-plateletcrit ratio—and overall survival might, in part, reflect underlying MGMT-related tumor biology." (PMID 41114777, 2025). "From a biological perspective, MGMT promoter methylation leading to gene silencing is not only associated with alkylating agent resistance but may also influence anti-angiogenic therapy by altering tumor angiogenesis characteristics." (PMID 40963873, 2025).
tumor (continued). "For this, incorporating genetic markers (e.g., IDH1 mutation, MGMT promoter methylation) with imaging features (e.g., signal intensity, diffusion metrics, perfusion parameters) was proposed, which provided a more accurate and dynamic measurement of tumor heterogeneity." (PMID 40432717, 2025). "Furthermore, in this study, we found that the frequency of MGMT expression was decreased in higher grade Pan-NET, suggesting that MGMT may be associated with a tumor suppressive effect in Pan-NET." (PMID 37161026, 2023). "Recent studies revealed that multiple factors including MGMT mutation, tumor immune microenvironment, inflammasome and PI3K/Akt pathways could contribute to individualized TMZ efficacy, whereas there still lack of strategies to increase the chemotherapy sensitivity." (PMID 36927689, 2023). "MGMT encodes a DNA repair enzyme that removes alkyl adducts from the O6 position of guanine in tumor DNA, which is damaged by alkylating agents, such as temozolomide, and converts the guanine in tumor DNA to O6-methylguanine, exerting antitumor effects by impairing DNA replication." (PMID 36291588, 2022). "However, MGMT loss is linked with an increased susceptibility to acquiring other mutations in both oncogenes and tumor suppressor genes, thus potentially stimulating tumor progression and poorer prognosis." (PMID 35621918, 2022). "The characteristic expression patterns of m5C-related lncRNAs were associated with MGMT promoter methylation, epithelial mesenchymal transition, tumor immune response, and cell cycle disruption and hypoxia, and it may also alter the sensitivity of tumor cells to TMZ-induced cytotoxic effects." (PMID 36437944, 2022). "However, Phase I trials showed that inhibitors that inactivate MGMT, improved the efficacy of BCNU (1,3-bis(2-chloroethyl)-1-nitrosourea) on tumor cells but were associated with more systemic toxicity, indicating MGMT expression is also vital for protecting from DNA damage in normal cells." (PMID 34711928, 2022). "However, some tumour cells are able to repair this type of DNA damage using a repair protein O6‐alkylguanine DNA alkyltransferase, which is encoded by the O‐6‐methylguanine‐DNA methyltransferase (MGMT) gene." (PMID 34477324, 2021). "Besides STR profiles, for each CTSC and GSC line, clinical data of the patients are reported such as tumor location, stage and mutations, MGMT methylation status and tumor proliferation index, MSI, expression of mismatch repair proteins and the expression of molecular markers." (PMID 33128777, 2021). "A study found that ill‐defined tumor borders, lower attenuation coefficients in computed tomography scans, lower fractional anisotropy, and increased apparent diffusion coefficient values are associated with MGMT promoter methylation in a mixed group of WHO grade III and grade IV patients." (PMID 34648115, 2021). "In addition to the clinical biomarkers, univariable analysis, which introduced the WHO grade as an additional interaction term and thus excluded its effects on tumor growth, suggested that the status of MGMT, TERT, and C250T were associated with tumor growth rate." (PMID 32388499, 2020). "Although MGMT-deficiency is particularly common in GBM, other tumor types also display MGMT deficiency; by rationally combining TMZ with a DDR-inhibiting agent (TRC102), the efficacy of TMZ might be extended to malignancies beyond GBM without requiring molecular testing." (PMID 33216844, 2020). "Silencing of a tumor suppressor gene such as MGMT might occur during tumor development, thereby creating a more genetically unstable cell and favoring DNA damage and mutations, which ultimately would lead to better adapted tumor cell clones." (PMID 31505812, 2019). "Besides, MGMT promoter methylation is prone to be associated with tumor necrosis (P = 0.028)." (PMID 29467012, 2018).